KEAP1 (kelch like ECH associated protein 1)
Diseases named in the same sentence as KEAP1 in open-access papers (continued):
Sharing a sentence is not in itself a finding about the gene and the disease.
cancer (continued). "In this work, we analyzed the influence of several DPP III mutations found in the cancer samples on the interaction with the Kelch domain of KEAP1 protein." (PMID 35216111, 2022). "In cancer, somatic loss of function mutations in KEAP1 or NFE2L2 genes are the most known mechanisms that reduce NRF2-KEAP1 binding and prevent degradation of NRF2 through KEAP1/CUL3/RBX1 E3-ubiquitin ligase complex." (PMID 33808001, 2021). "NRF2 stability is tightly controlled by Kelch-like ECH-associated protein 1 (KEAP1) in many cancer types." (PMID 34079797, 2021). "Loss of Keap1 function is shown to mediate Nrf2 stabilization and is often associated with reduced drug sensitivity in several cancers." (PMID 33419140, 2021). "Evidence has shown that the NRF2/KEAP1 signaling pathway is associated with the proliferation of cancer cells and tumerigenesis through metabolic reprogramming." (PMID 33922165, 2021). "To date, various mutations have been identified in Keap1 and Nrf2 genes in different types of human cancers." (PMID 34400968, 2021). "It has been reported that cancer cells with high NRF2 activation due to KEAP1/NRF2 mutation or KRAS activation depend upon serine and asparagine synthesis pathways for rapid proliferation and survival." (PMID 34247201, 2021). "According to a pan-cancer analysis, the amount of KEAP1 mutations in 40,167 patients with distinct cancer types was 2.7%; patients with NSCLC had the highest levels of KEAP1 mutations (15.8%)." (PMID 35070984, 2021). "As well as genetic mutations, Nrf2 hyper-activation in cancer can also arise as a result of epigenetic modifications of Keap1." (PMID 34202320, 2021). "In the context of Nrf2 interference with cancer chemotherapy, its status of anti- or pro-tumorigenic is defined by many different modalities, but mainly the loss of functional Keap1 or its mutation contribute to deregulation of Nrf2 in cancer cells." (PMID 34360990, 2021). "A recent study demonstrated that stimulating KRAS-driven LUAD cancer metastasis was induced by KEAP1 loss but NRF2 activation." (PMID 34226519, 2021). "High expression of Nrf2 in human cancer cells can due to somatic mutations in Keap1 or Nrf2, epigenetic silencing of Keap1, transcriptional upregulation of oncogene signaling related to Nrf2 and aggregation of Nrf2/Keap1 complex disrupting proteins." (PMID 34400968, 2021). "One of the major causes of aberrant activation of NRF2 in cancer cells is somatic mutation in KEAP1 or NRF2 (NFE2L2) genes." (PMID 32112372, 2020). "Somatic mutations identified in the NRF2 or KEAP1 genes of NRF2-addicted cancers cause the stabilization and accumulation of NRF2." (PMID 33375248, 2020). "Most epigenetic studies of KLHL family genes focused on cancer-associated promoter hypermethylation, especially, hypermethylation of the KEAP1 CpG island promoter during carcinogenesis or acquisition of drug resistance." (PMID 33182325, 2020). "As somatic mutations in KEAP1 occur across the entire gene and cause loss-of-function, it has been referred to as a tumour suppressor, and it has been proposed to drive cancers of the lung, head and neck, and liver." (PMID 33276631, 2020). "NRF2 activation in cancer cells is brought by not only somatic mutations in NRF2 or KEAP1 genes but also several unique mechanisms, including oncometabolites, exon skipping, and promoter methylation, in NRF2-addicted cancers." (PMID 33375248, 2020). "Given that the Kelch domain deletion showed the strongest effect on SOX9 binding, we examined three cancer‐associated KEAP1 mutations within this domain for their effects on SOX9 stability." (PMID 33173725, 2020). "Through our studies, a subset of cancer‐associated KEAP1 mutations was found to disrupt the substrate‐recruiting function of Kelch domain to impair the ability of KEAP1 to bind and promote SOX9 poly‐ubiquitination and degradation." (PMID 33173725, 2020).
cancer (continued). "Recent findings have indicated that NRF2 and its negative regulator KEAP1 are frequently mutated in cancer, and mutations have been also observed in UBC." (PMID 32455559, 2020). "Aberrant KEAP1 methylation was also reported in colorectal cancer cells and cancer tissues and was linked to a downregulation of its transcriptional activity and an upregulation of NRF2 and its target genes’ expression." (PMID 32971994, 2020). "Several causes have been described for the aberrant accumulation of NRF2 in cancer cells, including somatic mutations in KEAP1 or NRF2 genes, sequestration of KEAP1 by p62/SQSTM1 and electrophilic attack of KEAP1 thiols by fumarate." (PMID 33219226, 2020). "In cancer, loss of KEAP1 function leads to enhanced activity of NRF2 and antioxidant-related element (ARE)-driven gene expression, thus promoting cellular resistance to oxidative stress, rapid proliferation, and metabolic deregulation." (PMID 32971994, 2020). "Recent studies have indicated that Keap1-Nrf2 pathway is engaged in sustaining CSC (cancer stem cell)-like properties in cancers and causes resistance to therapeutic agents." (PMID 32814771, 2020). "A prevalence and prognostic value of Keap1 and Nrf2 mutations are well known in cancer including HNSCC6–8." (PMID 33087706, 2020). "They found that NFE2L2/KEAP1 mutations are present in various cancers, with the highest incidence found in lung squamous cell carcinoma." (PMID 33228209, 2020). "Comprehensive genomic analyses have identified somatic mutations in the NRF2 and KEAP1 genes in various types of cancer." (PMID 32751080, 2020). "Overall, these results suggest a pathogenic role for SOX9 in promoting tumorigenesis downstream of cancer‐specific KEAP1 mutations." (PMID 33173725, 2020). "Further studies have shown that ML385 exerts selective cytotoxicity against cancer cells with Keap1 mutations and increases the toxicity of carboplatin in vitro and in vivo." (PMID 31511020, 2019). "More importantly, the mutations in Keap1 and constitutive activation of Nrf2 are frequently observed in various cancers, including PC, the safety and feasibility of using Nrf2 activators for treating PC should be carefully examined." (PMID 31511020, 2019). "These in vitro analyses showed that K‐563 was able to inhibit cell growth in Keap1‐ or Nrf2‐mutated cancer cells by Keap1/Nrf2 pathway inhibition." (PMID 30735010, 2019). "At the DNA level, methylation in the Keap1 promoter, epigenetic silencing of its targeted genes, or mutations present in the binding sites of Keap1–Nrf2 take place during cancer development, but also under selective pressure of different therapies." (PMID 31717324, 2019). "K‐563 also inhibited the expression of downstream target genes in other Keap1‐ or Nrf2‐mutated cancer cells." (PMID 30735010, 2019). "The KEAP1/NRF2 pathway has been widely investigated in tumors since it was implicated in cancer cells survival and therapies resistance." (PMID 31126053, 2019). "The further investigation to find more potent derivatives from K‐563 or an investigation of the mechanism through which K‐563 exerts its activity is expected to lead to the development of anti‐cancer agents for Keap1‐ or Nrf2‐mutated cancer patients." (PMID 30735010, 2019). "Functional Keap1 mutations have been detected in various cancers, and these mutations lead to upregulation of Nrf2 / ARE gene transcription." (PMID 31752777, 2019). "Further, NRF2 and KEAP1 mutations are common in many cancers and lead to impaired NRF2 degradation and constitutive NRF2 accumulation, thereby promoting glutathione (GSH) synthesis, detoxification of reactive oxygen species (ROS) and proliferation." (PMID 31107239, 2019). "Dysregulation of the Kelch-like ECH-associated protein 1 (Keap1)-Nrf2 pathway has been showed in experimental and human tumors, suggesting its possible role in cancer development." (PMID 31357662, 2019).
cancer (continued). "Tumorigenic mutations of Keap-1 and Nrf2 typically result in activation of Nrf2 targets, indicating the important role of Nrf2 in cancer." (PMID 29716554, 2018). "As a result, CP induced oxidative stress in cancer cells, which strongly suppressed the growth of tumors with Keap1 mutation and high Nrf2 activity." (PMID 30687097, 2018). "Mounting evidence revealed a darker side to Nrf2 in cancer, with many tumour types displaying elevated levels of the transcription factor, often due to loss-of-function mutations in the Keap1 gene that promote Nrf2-driven transcriptional activity." (PMID 29930754, 2018). "For example, somatic mutations that activate NRF2 or inhibit KEAP1-mediated degradation of NRF2 have shown prevalence in many cancers." (PMID 28793787, 2018). "Keap1 mutations activating NRF2 or mutations in NRF2 gene itself are frequent events in many cancer types." (PMID 29755668, 2018). "Several studies have identified inactivating mutations in Keap1, leading to an increase in Nrf2 function, in human cancers." (PMID 29618945, 2018). "Dysfunction of the KEAP1/NRF2 axis by genetic mutations is gradually becoming a milestone to understand cancer development, progression, and resistance to conventional and biological treatments." (PMID 29643973, 2018). "In cancer cells on the other hand, increased Nrf2 activation due to Keap1 or NRF2 mutations occurs frequently and this seems to be important in the maintenance of these cells." (PMID 30687097, 2018). "Deregulation of the KEAP1/NRF2 axis is actually considered a hallmark in cancer cells, since KEAP1 and NRF2 can modulate oncogenesis, cell proliferation, apoptosis, and tumor cell growth." (PMID 29643973, 2018). "Apart from mutation sites and gene expression changes, the overrepresentation of NRF2 and KEAP1 mutations in tumor types with known association with carcinogen exposure provides a glimpse into the roles of NRF2 in cancer development and progression." (PMID 30150714, 2018). "In contrast, the inhibition of Nrf2 by either Keap1 overexpression, Nrf2-small interfering RNA or by an Nrf2 depleting drug leads to anti-cancer drug susceptibility of these cells." (PMID 29261130, 2017). "Aberrant NRF2 activation in cancer cells occurs through somatic mutations in the KEAP1 or NRF2 gene as well as through other mechanisms that disrupt the binding of KEAP1 to NRF2." (PMID 28523248, 2017). "Because KEAP1 and Nrf2 are mutated in many cancer types, particularly in chemotherapy-resistant tumors, targeting pathways that do not rely upon a wild type KEAP1 to suppress Nrf2 is necessary for successful drug development." (PMID 28383481, 2017). "Cancers with loss of KEAP1 pose a serious complication for clinical treatment due to the NRF2-related etiology of the resistance to classical treatments." (PMID 28453520, 2017). "In different cancer cells, the mutation of Nrf2 and/or Nrf2-associated inhibitors Keap1 made the increase of Nrf2." (PMID 28035058, 2017). "Mutations in KEAP1 or NRF2 were found in approximately 0.9% of all cancer samples examined in studies published in COSMIC 2016." (PMID 28523248, 2017). "In other cancer types, KEAP1 mutations in the first Kelch domain (e.g., G333C in A549 cells) and in the intervention region (IVR, D236H in H460 cells) modified NRF2 signalling and influenced platinum sensitivity." (PMID 28767070, 2017). "The cancer cell line most susceptible to VSVΔ51-mediated cell killing was the human lung epithelial A549 line that harbors a point mutation inactivating Keap1, thus increasing Nrf2 nuclear translocation and transcriptional activity." (PMID 28527723, 2017). "In humans, genetic polymorphisms and expression of Keap1 and Nrf2 are associated with tumorigenesis and clinical outcomes in cancer patients." (PMID 28886135, 2017). "KEAP1 promoter epigenetic silencing as just reported in cancers as well as in the other diseases with a clear association with tumors having a low incidence of somatic mutations." (PMID 28061437, 2017).
cancer (continued). "In recent years, frequent mutations in the NFE2L2/KEAP1/CUL3 pathway had been reported in many types of cancers, including ESCC10,18–21." (PMID 29127303, 2017). "This is of potential concern since somatic mutations in Keap1 and Nrf2, resulting in a constitutively active Nrf2 pathway, have been reported in some cancers and confer high tolerance to anti-cancer drugs." (PMID 29150527, 2017). "Keap1 somatic mutations have been linked to chemoresistance in various carcinomas, although Keap1 protein expression in this context is less studied." (PMID 29348788, 2017). "Since then, Keap1 mutations have also been found in several other cancer types, such as NSCLC, gallbladder, ovarian, and liver cancers." (PMID 27200299, 2016). "Somatic mutations in KEAP1 gene in cancer tissues and cancer-derived cell lines of different origins affect the repressive activity of KEAP1, stimulate the nuclear accumulation of NRF2, and provide advantages for cell growth." (PMID 27703446, 2016). "Among them, somatic mutations in the components of Keap1–Nrf2 pathway have been found in many cancer types." (PMID 27200299, 2016). "Several mechanisms have been shown to be involved in the constitutive activation of Nrf2 in cancer cells, mainly gain-of-function mutations in Nrf2 and loss-of-function mutations in Keap1." (PMID 27418953, 2016). "Mutations in Nrf2 and Keap1 are known to occur in various cancer cell lines and to confer protection to cancer cell lines toward chemo- or radiotherapy." (PMID 27047795, 2016). "Several mechanisms have been shown to be involved in the constitutive activation of Nrf2 in cancer cells, mainly gain-of-function mutations in Nrf2 and loss-of-function mutations in Keap1, leading to an impairment of the binding to Keap1." (PMID 26697129, 2016). "Many cancers express gain-of-function Nrf-2 mutants or loss-of-function Keap1 mutations that lead to constitutive Nrf-2 activation, which contributes to the resistance against oxidative stress, such as chemotherapeutic drugs and ionizing radiation." (PMID 26124081, 2015). "On the contrary, in diverse types of cancer, loss of function of Keap1 was observed to assure prolonged activation of Nrf2, thereby upregulating its downstream genes and subsequently facilitating the growth of neoplastic cells." (PMID 26694419, 2015). "The Kelch domain structures also help to explain the effects of somatic cancer mutations identified in Keap1, as well as those in Nrf2, which cluster to the DLG and ETGE motifs." (PMID 26057936, 2015). "In cancer tissues and cells, loss of Keap1, an Nrf2 negatively regulator, leads to nuclear localization and constitutive activation of Nrf2." (PMID 26194347, 2015). "Previous work has demonstrated that brusatol is able to deplete Nrf2 in cancer cell lines harboring wild-type or mutated Keap1." (PMID 25445704, 2015). "Paradoxically, recent papers have suggested a dark side of Nrf2 that consist in the ability of cancer cells to acquire a growth advantage thank to the loss of Keap1 leading therefore to Nrf2 activation." (PMID 25699252, 2015). "Taken together, these data are consistent with the notion that loss of KEAP1 affects multiple targets that are relevant to cancer cell biology, including not only NRF2, but also IKKβ and BCL2." (PMID 26301506, 2015). "Fifth, certain cancer metabolites, such as fumarate, can modify KEAP1 protein, causing it to activate NRF2." (PMID 25226504, 2014). "Keap1 mutation or p62 accumulation leads to a constitutively active Nrf2, which contributes to the growth of cancer cells." (PMID 24681637, 2014). "First, somatic mutations on KEAP1 or NRF2 have been reported to cause of gain-of-function NRF2 in cancer cell lines and tumor tissues." (PMID 25226504, 2014). "Investigators have reported hypermethylation in CpG islands of KEAP1 which were associated with reduced KEAP1 expression in human cancers from lung, prostate, colon, and so forth." (PMID 23936606, 2013).
cancer (continued). "To date, numerous mutations have been found of both Keap1 and Nrf2 in various human cancers resulting in the constitutive expression of prosurvival genes." (PMID 23766865, 2013). "As KEAP1 gene mutations have been reported in other types of human cancer, we sequenced all protein-coding exons in 10 CRC cell lines." (PMID 22325485, 2012). "Inversely, downregulation of the Nrf2-dependent response by overexpression of Keap1 or transient transfection of Nrf2-small interfering RNA (siRNA) rendered cancer cells more susceptible to these drugs." (PMID 23119185, 2012). "Missense mutations in the KEAP1 gene have been identified in several human cancers, particularly in solid tumors in the lung, gallbladder and liver." (PMID 23272301, 2012). "Whereas this study utilized cell permeable fumaric acid esters (mono- and dimethylfumarate), we have demonstrated that pathophysiological levels of fumarate associated with cancer are sufficient to succinate KEAP1 and activate Nrf2 signaling." (PMID 22014577, 2011). "To date, numerous mutations have been found of both Keap1 and Nrf2 in human cancers leading to constitutive expression of pro-survival genes." (PMID 24212776, 2011). "The Keap1-Nrf2 signaling pathway is a central regulator of transcriptional responses to oxidative stress and is strongly linked to diverse pathologies, particularly cancer." (PMID 41596192, 2026). "Across pan-cancer analyses, while KEAP1 mutations were enriched in KRAS G12C tumors (15.38% vs. 4.61% in non-G12C), this pattern was less pronounced in NSCLC-specific contexts, likely attributable to overlapping mutational landscapes and tissue-specific selection pressures." (PMID 41541668, 2026). "Hence, the Keap1/Nrf2/xCT signaling pathway, a master regulator of cysteine metabolism, is frequently mutated in cancers and can be activated by oncogenic drivers such as KRas and PI3K, underscoring its critical role in tumorigenesis." (PMID 40535116, 2025). "Moreover, pan-cancer analyses have revealed recurrent co-mutations in KEAP1, NFE2L2, and NOTCH1, supporting a cooperative role in driving tumor progression." (PMID 40563292, 2025). "KEAP1, frequently mutated in cancer, functions as a tumor suppressor." (PMID 39935430, 2025). "Given that NRF2 is frequently activated in HCC and other cancers via KEAP1 mutations or oxidative stress, such tumor clusters could represent functionally relevant subpopulations in cancer progression." (PMID 40818321, 2025). "Mutations in KEAP1 have been linked to immune therapy response and chemoresistance in cancer." (PMID 40228435, 2025). "Cysteine’s antioxidant function is further exemplified by its contribution to glutathione biosynthesis, a tripeptide that is notably enriched in cancer cells and is predominantly synthesized in response to Keap1/Nrf2/xCT activation induced by oncogenic mutations." (PMID 40535116, 2025). "We posit that the anti-cancer benefit derived from systemic triterpenoid treatment targeting TIME cells will outweigh the cancer cell survival advantage since the cancer cells will likely have already achieved maximal NRF2 pathway activation through genetic KEAP1 mutation." (PMID 41462606, 2025). "However, in cancer, sustained activation of Nrf2, often driven by mutations that impair its repressor Keap1, can promote tumor progression, chemoresistance, and escape from ferroptosis." (PMID 41415550, 2025). "Although the detailed mechanism is waiting to be elucidated, as a significant character of a subgroup of KRAS-mutated cancer cells, KEAP1 could have a crucial role in shaping global characteristics, or at least as a substantial component." (PMID 40611261, 2025). "Specifically, as cancers with pre-existing KEAP1 or NFE2L2 mutations exhibit constitutive NRF2 activation, they will not benefit from NRF2 induction by G12Ci drugs, while in contrast, tumours with wild-type KEAP1-NRF2 will benefit from G12Ci-induced NRF2 activation." (PMID 40890297, 2025).